IL33 (interleukin 33)
Diseases named in the same sentence as IL33 in open-access papers (continued):
Sharing a sentence is not in itself a finding about the gene and the disease.
Obesity (continued). "Thus, IL-33 had a protective effect against obesity, insulin resistance and diabetes in animal models due to the reduction of resistin expression, accumulation of Th2 cells and IL-5, IL-13 and the suppression of T effectors cells by IL-10 releasing." (PMID 32824505, 2020). "Our primary goal was to determine whether IL-33 contributes to pulmonary responses to O3 in mice with obesity induced by HFD feeding." (PMID 32326950, 2020). "Indeed, two recent studies have found that IL-33 and IL-18, which suppress obesity and metabolic dysfunction, can in fact act to limit A. muciniphila abundance in mice under certain settings." (PMID 31488830, 2019). "Overall, these results suggest that IL33/ST2 might counteract obesity IR through its proliferative actions on Tregs." (PMID 30158466, 2018). "IL-33 contributed to obesity-related increases in the response to O3: BAL IL-33 was greater in obese than lean O3 exposed mice and anti-ST2 reduced O3-induced increases in baseline mechanics, in airway responsiveness, and in BAL neutrophils in obese but not lean mice." (PMID 27472835, 2017). "Obesity and O3 also interacted to induce type 2 cytokine expression in ILC2s and γδ T cells, and these cells appear to contribute to the effects of IL-33, though other cellular targets of IL-33 may also be involved." (PMID 27472835, 2017). "IL-33 can improve metabolic parameters through restoration of ST2+ Treg cells and accumulation of anti-inflammatory (M2) macrophages in the adipose tissue of obese mice, which are associated with an improvement of obesity-induced insulin resistance." (PMID 28611297, 2017). "In addition, recent research revealed that group 2 innate lymphoid cells were necessary to the IL-33-induced beiging of white adipose tissue and the limiting of obesity through IL-4 receptor signaling, accompanied with the up-regulation of Ucp1 expression." (PMID 28806763, 2017). "Elevations in fatty acids in the lungs of db/db mice would also be expected to increase the ability of ILC2s to produce type 2 cytokines, and we have reported that IL-33 causes ILC2 activation and type 2 cytokine release are important for obesity-related increases in the response to O3." (PMID 28704544, 2017). "Indeed, IL-33 is rapidly becoming accepted as an important factor in limiting obesity and metabolic dysregulation with several groups identifying a central role for IL-33 in metabolism." (PMID 26490658, 2016). "Recent discoveries have identified that innate lymphoid cell 2 subset (ILC2s) dysregulation is a conserved feature of obesity and manipulation of the IL-33/ILC2 axis may lead to therapies for this disease." (PMID 25852681, 2015). "The metabolic effects of IL-33 in obesity have mostly been investigated in murine models." (PMID 24886535, 2014). "The aim of this study was to highlight the expression and the effects of IL-33/ST2 system, and particularly of sST2 in VSMCs and to determine whether sST2 could be a new biotarget reducing vascular remodeling associated with obesity." (PMID 24265755, 2013). "More recently, a newly identified population of cells expressing ST2 were found in adipose named natural helper cells or fat-associated lymphoid cluster (FALC) cells that produce large amounts of Th2 cytokines in response to IL-33, but the direct role of these cells in obesity is still unclear." (PMID 21871091, 2011). "However, IL-33 has shown various protective effects in cardiovascular diseases such as atherosclerosis, obesity, type 2 diabetes and cardiac remodeling." (PMID 21871091, 2011). "However, our HFD-induced obesity model showed significantly decreased IL-33 expression." (PMID 40509380, 2025). "While inflammation connects obesity and cancer, it is not yet clear whether IL-33 contributes to cancer associated with obesity." (PMID 40236667, 2024). "Therefore, the impact of endogenous IL-33 on obesity remains veiled." (PMID 38632591, 2024). "However, the IL-33/ST2 pathway is thought to be protective during obesity." (PMID 40236667, 2024).
Obesity (continued). "However, it remains uncertain whether IL-33 is indeed expressed in adipose tissue dendritic cells (ATDCs) and whether it can mediate Treg regulation, particularly in the context of obesity." (PMID 38566998, 2024). "Hence, we explored how IL-33 played a role in the development of obesity." (PMID 38632591, 2024). "Moreover, both gain and loss-of-function models involving IL-33 or ST2 have demonstrated specific alterations to the Treg populations in VAT, indicating IL-33/ST2 axis as a crucial mechanism to control Treg populations during obesity." (PMID 38566998, 2024). "Moreover, the statistically significant correlation between high BMI and high platelets, high SII, high NT-proBNP, and high ST2/IL-33 marks a cross-link between obesity, thrombosis, systemic inflammation, myocardial inflammation, and myocardial wall stress unrelated to 131I therapy." (PMID 39795891, 2024). "However, some controversies exist, and the role of IL-33 in obesity is still a matter of debate." (PMID 36768322, 2023). "Therefore, the failure of enhanced IL-33 to combat obesity and related insulin resistance could be related to the dysfunction of ILC2s." (PMID 37138165, 2023). "In addition, aging-, obesity-, inflammation- or allergy-induced IL33 fluctuation could directly target BM EoPs and/or tissue eosinophils and modulate their number and activation." (PMID 38567054, 2023). "IL-33 treatment contributes to homeostasis in the adipose tissue by facilitating the differentiation and maintenance of Foxp3+ST2+ Treg cells and ILC2 in visceral adipose tissue, an immunomodulatory effect that can contribute towards down-regulating obesity-associated inflammation." (PMID 35807067, 2022). "Additionally, IL-33 has been shown to be protective in obesity." (PMID 35844529, 2022). "Meanwhile, studies have also reported that IL-33 may play an undetermined role in obesity and its cardiovascular or diabetic complications since the specific role of IL-33 in the pathogenesis and development of several metabolic diseases seems to be inconsistent." (PMID 33541367, 2021). "In addition, IL-33 was positively correlated with metabolic syndrome risk factors such as dyslipidemia and hypertension rather than obesity itself." (PMID 33541367, 2021). "Therefore, it is urgently needed to clarify whether systemic level and tissue level of IL-33 is differentially regulated by obesity." (PMID 33541367, 2021). "Similarly, IL-33 is proposed to protect against the adipose tissue inflammation of obesity." (PMID 32326950, 2020). "Moreover, in some clinical studies IL‐33 concentrations showed different behavior in health and disease, suggesting a downregulation in some chronic inflammatory diseases such as type 2 diabetes and obesity, limiting inflammatory damage." (PMID 31880859, 2020). "This study reveals a new mechanism by which the IL-33/ST2 axis regulates the differentiation of preadipocytes and provides a new idea for improving obesity prevention." (PMID 39596071, 2024). "The complex interactions between the IL-33/ST2 axis in adipose tissue and the tumor microenvironment (TME) deserve a thorough investigation, especially concerning obesity-related tumors." (PMID 40236667, 2024). "IL-33 is a key inducer of ILC2, and ILC2 in WAT can promote WAT browning and help prevent obesity development." (PMID 38365763, 2024). "In conclusion, we improved the knowledge on IL-33/ST2, suggesting the involvement of these proteins in the obesity axis, and we highlighted for the first time a modulation driven by ghrelin—paving the way for future mechanistic studies." (PMID 36768322, 2023). "Accordingly, mice overexpressing CCL11 in AT, or the administration of IL33 restored ATE fraction and suppressed obesity." (PMID 38567054, 2023). "Firstly, we showed that obesity determined a dysregulation of the IL-33/ST2 pathway characterized by an opposite relation between weights and circulating IL-33 levels in Lean versus Obese animals." (PMID 36768322, 2023).
Obesity (continued). "Here, we evaluated IL-33/ST2 expression and function related to cardiac fibrosis development in a rat animal model of obesity, the Zucker fatty rat." (PMID 36768322, 2023). "In obesity, TNF triggers IL-33-dependent expression of PD-1 on ILC2s and further recruits and activates PD-L1hi M1 macrophages." (PMID 35574038, 2022). "IL33, another member of the IL1 cytokine family, was proved to play a protective role in the setting of obesity and type 2 diabetes mellitus." (PMID 34207683, 2021). "In the adipose tissue, PD-1 is upregulated in IL-33-activated ILC2s in response to TNF-α, present in high concentrations due to obesity." (PMID 34489979, 2021). "There is a prominent role for IL-33 in regulating metabolic homeostasis, and disruption of the Treg-ILC2-Macrophage axis contributes to increased inflammation and obesity." (PMID 33708206, 2021). "However, the extent to which this loop contributes to obesity, remains unclear as the conditional loss of function of IL-33 from mesenchymal stromal cells has no impact on body weight nor adiposity." (PMID 34613819, 2021). "In the case of long-term obesity or HFD, the results of these studies seem to point towards induction of IL-33 to engage the early steps of type 2 immunity through activating ILC2s." (PMID 34489979, 2021). "A recent study reported an increase of IL-33 and ST2 expressions in adipocytes and adipose tissues as well as in endothelial and epithelial cells in obesity." (PMID 32824505, 2020). "ILC1-derived IFN-γ balanced out the effect of IL-33 mediated ILC2 activation within visceral AT, providing an in situ negative regulators of ILC2 anti-obesity effects." (PMID 32581740, 2020). "We have previously reported that both IL-33 and TNF play a role in the effects of obesity on O3-induced AHR." (PMID 28704544, 2017). "The findings regarding IL-33 serum levels in both patients with T2D and nondiabetic individuals with obesity versus healthy controls are inconclusive." (PMID 39171751, 2024). "The disruption or removal of any component within the IL-33/ILC2/Eosinophil axis leads to heightened adipose tissue inflammation and facilitates the development of insulin resistance in response to diet-induced obesity (DIO)." (PMID 39335642, 2024). "Investigating IL-33 in obese individuals, both with and without T2D, can provide valuable insights into how IL-33 levels change as obesity progresses to T2D." (PMID 39171751, 2024). "Here, it was reported that patients with obesity, with or without diabetes, had higher baseline IL-33 levels compared with healthy controls." (PMID 39171751, 2024). "Serum IL-33 levels were compared between nondiabetic individuals with obesity and healthy controls across six studies, involving a total of 327 patients." (PMID 39171751, 2024). "NEW & NOTEWORTHY Our research finds an inconclusive relationship between IL-33 serum levels in individuals with type 2 diabetes (T2D) and nondiabetic individuals with obesity." (PMID 39171751, 2024). "Although not reaching statistical significance, the results consistently indicated a negative effect, suggesting a potential reduction in serum IL-33 levels among individuals with T2D and obesity compared with healthy controls." (PMID 39171751, 2024). "Here, meta-analysis does not provide conclusive evidence of significant differences in IL-33 serum levels between individuals with T2D or nondiabetic obesity and healthy controls." (PMID 39171751, 2024). "Despite this, there is a lack of research on IL-33 in the context of obesity-related cancer, particularly regarding the mechanisms by which IL-33 influences these cancers." (PMID 40236667, 2024). "Conversely, stimulation of adipose tissue with obese-derived VAT determined a slight reduction in the expression of ST2L while soluble sST2 did not vary, suggesting deregulation in IL-33/ST2L pathway due to obesity." (PMID 36768322, 2023).
Obesity (continued). "In this regard, the role of IL-33/ST2 pathway disbalance in obesity as a protective factor or negative mediator of cardiac remodeling has yet to be elucidated." (PMID 36768322, 2023). "Of note, sST2, a recently discovered adipokine induced by obesity, was blocked by IL-37D transgene in HFD-fed mice, indicating that sST2 may be a potential target for IL-37D to regulate IL-33/ST2 signaling." (PMID 35383145, 2022). "In light of the rescue effect of IL-33 on VAT-Tregs from obese mice, therapeutic administration of IL-33 may enhance the expansion and function of VAT-Tregs in obesity patients." (PMID 35720275, 2022). "Changes in other IL-33 responsive cell types, such as ILC2s and mast cells were also observed following obesity, failed to recover with WL, and were exacerbated by WC." (PMID 35618862, 2022). "Furthermore, we investigated the source of IL-33 and IL-25 responsible for ILC2 activation in the context of a chronic low-grade inflammation such as diet-induced obesity and metabolic syndrome." (PMID 30755607, 2019). "In obesity, Th1 inflammation mediated by obese adipocyte- or macrophage-expressed MHCII may contribute to the reduction in adipose Treg in diet-induced obesity via producing IFN-γ, which blocks the effects of IL-33 on Treg proliferation." (PMID 30619305, 2018). "Obesity and ozone also interacted to promote type 2 cytokine production in γδ T cells and ILC2 in the lungs, which may contribute to the observed effects of IL-33." (PMID 27472835, 2017). "Furthermore, our findings indicate that IL-33 derived from VAT DCs plays a critical role in mediating decreased Treg differentiation in obese situations, shedding light on depot-specific regulation of tissue inflammation and homeostasis in obesity." (PMID 38566998, 2024). "Furthermore, we confirmed that other APCs showed no significant changes in Il33 mRNA expressions in obesity." (PMID 38566998, 2024). "The different methodological approaches consistently suggest that there is not enough evidence to reject the null hypothesis in the comparison of serum IL-33 levels between nondiabetic individuals with obesity and healthy controls." (PMID 39171751, 2024). "Similarly, the meta-analysis did not reveal a significant difference in IL-33 levels in nondiabetic individuals with obesity compared with to healthy controls." (PMID 39171751, 2024). "Furthermore, our results also revealed several common upstream regulators associated with immune regulation and resistance to obesity (IL-4, IL-5, IL-33, CD15, HGF, ANGPT2, VEGFA, and neuropilin 1 [Nrp1]), supporting a critical role of intestinal homeostasis in systemic pathogenesis of obesity." (PMID 36880999, 2023). "However, interleukin-33 has shown various protective effects in CVD, obesity and diabetes." (PMID 36614933, 2022). "Finally, most previous studies have shown that exogenous IL-33, rather than endogenous IL-33, can regulate glucolipid metabolism and inflammation in obesity." (PMID 33541367, 2021). "Importantly, increased production of IL-33 by VAT mesenchymal stromal cells is not sufficient to rescue VAT function in obesity." (PMID 34631704, 2021). "sST2 overproduction may explain the lack of Treg response to the elevated IL-33 produced during obesity." (PMID 34631704, 2021). "Indeed, IL33 and ST2 are also expressed in human WAT and population-based studies have found positive correlations between increased serum levels of the IL33 soluble decoy receptor (sST2) and obesity, T2DM and their metabolic complications." (PMID 30158466, 2018). "However, IL-33 was shown to have various protective effects in CVD, obesity and diabetes." (PMID 28977161, 2017). "Sensitivity analyses of IL-33 serum levels in nondiabetic individuals with obesity versus healthy controls involving the exclusion of individual studies in the comparison group of individuals with obesity versus healthy controls revealed notable changes in the pooled MD and heterogeneity measures." (PMID 39171751, 2024).
Obesity (continued). "Moreover, there is evidence to suggest that circulating IL-33 may confer protective metabolic effects in humans, more specifically, in individuals with normal weight and glycemia but not with obesity and/or T2D." (PMID 31073344, 2019). "Related studies have found increased obesity and worsened metabolic profiles in mice lacking ST2 or IL-33." (PMID 38365763, 2024). "Obesity per se may increase AHR without inflammation and the increase in mucus and inflammation by IL-33 combined with leptin enhanced AHR in obesity." (PMID 34074279, 2021). "In addition, recent evidence suggests that circulating IL-33 may confer protective metabolic effects (body mass index (BMI), lipid profile, and glycated hemoglobin (HbA1c)) in humans, specifically, in individuals with normal weight and glycemia but not in those with obesity and/or T2D." (PMID 31073344, 2019).